CD28 (CD28 molecule)
Diseases named in the same sentence as CD28 in open-access papers (continued):
Sharing a sentence is not in itself a finding about the gene and the disease.
tumor (continued). "We next evaluated CD28 and 4-1BB MSLN CAR T cells antitumor potency against K562 tumor cells expressing GFP and MSLN after 3 GC exposures (10 μg/ml Dx and 50 μg/ml MP) over a one-week period using a flow cytometry based killing assay." (PMID 38475830, 2024). "Research has shown that tumour-derived γδ Tregs can induce phenotypic changes in T cells, such as the downregulation of CD27 and CD28, leading to the senescence of responsive T cells." (PMID 39678507, 2024). "This mode of “split costimulation” of the CD28 signal and 4-1BB signal makes CAR-T anti-tumor efficacy better and has been confirmed to be universal." (PMID 39575257, 2024). "B7H3 CAR-T cells with the TMIGD2 co-stimulatory domain exhibited superior anti-tumor activity, enhanced expansion, and improved persistence compared to traditional CAR-T cells incorporating CD28 and/or 4-1BB co-stimulatory domains." (PMID 39506843, 2024). "This was also accompanied by the upregulation of proliferation marker MKI67, costimulatory genes (CD28, TNFRSF9 (4-1BB), and tumor-reactivity markers (e.g., ENTPD1/CD39, ITGAE/CD103) suggestive of an anti-tumor response in face of rising tumor levels." (PMID 37919606, 2024). "In pre-REP, TILs resident in tumour fragments receive—in addition to IL-2—signals through the T cell receptor (TCR) and possibly through co-stimulatory CD28 from adjacent tumour-resident antigen-presenting cells." (PMID 38658764, 2024). "Interestingly, we found that introducing Let-7i to tumours resulted in enhanced CD86 expressions in APCs in the draining LNs, an important costimulatory molecule that activates and differentiates T cells through interaction with CD28 and is associated with improved APC function." (PMID 38554167, 2024). "First-generation CARs composed of the CD3ζ chain and second-generation CARs composed of CD28 and CD3ζ, 4-1BB and CD28, 4-1BB and CD3ζ, 4-1BB, CD28 and CD3ζ, or CD137 and CD3ζ were applied to redirect NK cells against tumor cells." (PMID 38443448, 2024). "The development of second-generation CAR-T featuring costimulatory domains (CD28, 4-1BB, and OX40) has resulted in substantial cell expansion and heightened tumor activity." (PMID 39697210, 2024). "We isolated tumor infiltrated CD8 cells and stimulated with anti-CD3/anti-CD28 Abs ex vivo only for a short period of time to stimulate only those cells that were actively producing IFNγ in vivo." (PMID 38789421, 2024). "PBMCs were isolated at day 50 from IP tumor-bearing mice and activated with anti-CD3/CD28 for 24 h, then analyzed by flow cytometry to determine the extent of T-cell activation, and expression of key transcription factors and effector molecules." (PMID 38235131, 2023). "The transition from the periphery to the NT tissue and the tumor site revealed a different phenotypic distribution of CD8+ T cells according to their PD1 and CD28 expression." (PMID 37898752, 2023). "Compared with CD3ζ, CD28-CD3ζ, DNAM1-CD3ζ and 2B4-CD3ζ, CAR-NK expressing DNAM1-2B4-CD3ζ chimeric antigen receptor has the best anti-tumor effect." (PMID 37404752, 2023). "CD28 and CD3 ζ signaling domains, along with the 4-1BB ligand, would provide optimal costimulatory support to enhance the anti-tumor efficacy and prolong the persistence of CAR-T cells." (PMID 37304291, 2023). "It is widely supported that the co-stimulatory domain, typically CD28 or 4-1BB, can greatly impact CAR T-cell functionality and in vivo expansion and persistence for durable anti-tumor responses." (PMID 37550294, 2023).
tumor (continued). "Correlations between the upregulation of CD80, CD86, and CD28 have been found in OSCC, and the lack of change in CD28 and PD-1 transcripts in our tumor samples, which might have been associated with the complexity in CTLA4 abundancy, requires further stratification." (PMID 36983005, 2023). "We detected ex-vivo CXCL13 production mainly in CD8+ T cells from the tumor site, significantly highest in PD1+CD28− TRM." (PMID 37898752, 2023). "These CD26 2G (CD28) CAR-T-cells displayed cytotoxicity against CD26-positive malignant cells, activated multiple effector functions in co-culture assays, and limited tumor progression in a mouse model." (PMID 37626869, 2023). "In this study, we developed PAR1-targeted CAR-T cells using third-generation CARs containing additional signaling domains, including CD28, CD137 (4-1BB), and CD3ζ (CD247), to augment activation of cytokine production and a tumor-eradication ability." (PMID 37667257, 2023). "CD28 and CTLA4 expressed on T lymphocytes share identical ligands, CD80 and CD86, on tumor cells or antigen-presenting cells." (PMID 36983005, 2023). "Together, these results suggest that, compared to anti-CD3/CD28 restimulation, restimulation by IR HNSCC tumor cells more accurately represents T cell anti-tumor immune responses during experimental HNSCC carcinogenesis." (PMID 37444444, 2023). "There are multifactorial potential interactions between T-ALL and stroma that shape the myeloid anti-tumor immune response, including between CD47/SIRPα, PD-L1/PD-1, CD40/CD40L, and CD28/CD80/86." (PMID 36897988, 2023). "It has been suggested that the IL-15-conjugated CD28-CAR structure reduces exhaustion markers, upgrades persistence, and enhances the anti-tumor function of CAR-NKT cells." (PMID 37158883, 2023). "In conclusion our work highlights how the co-stimulatory molecule CD28 is crucial in dictating different functional states in PD1+ CD8+ T cells in peripheral blood and tumor site of NSCLC patients." (PMID 37898752, 2023). "Amplification of CD28+ T cells within the TME can enhance their antitumor effects and facilitate tumor cell elimination." (PMID 37749625, 2023). "To determine the function of B cells in dLNs of tumor-bearing mice, we evaluated their ability to suppress IFNγ production of T cells in response to anti-CD3/CD28 stimulation in vitro." (PMID 37291146, 2023). "Moreover, ITAM mutants could calibrate CD28-based CAR-T cells’ activation, through which CAR-T cells can be guided to various fates, allowing a CD28-based CAR-T cell with mutations in ITAM1 and ITAM2 domains to maintain long-lasting memory but retain efficient anti-tumor function." (PMID 37444586, 2023). "All but one (ARG1) of the proteins with significantly lower expression at baseline in the p16+ tumour group also showed lower expression at 12 months—that is, PTN, TNFRSF12A, CD28, and CD70." (PMID 36835246, 2023). "In an orthotopic mouse model of pleural mesothelioma, high doses of both CD28- and 4-1BB-based second-generation CAR T cells eradicated tumors effectively, whereas PD-1 upregulation in the tumor microenvironment inhibited T cell function." (PMID 37457699, 2023). "They discovered that GPC2 antigen density was below the threshold required for anti-tumor efficacy in traditional GPC2-CAR-T cells and modified them using CD28 co-stimulatory endodomains." (PMID 36853475, 2023). "Using L1CAM-specific CAR-T cells, the short spacer-CD28/ζ CAR design showed maximum expansion at the tumor site and initiated tumor regression in mouse xenograft models." (PMID 38516299, 2023). "These cells are unable to respond to stimulation or recognition of tumor antigens because of the downregulation of the co-stimulatory molecules CD27 and CD28 and the upregulation of inhibitory molecules, including LAG-3 and PD-1." (PMID 38136380, 2023).
tumor (continued). "They intraperitoneally injected anti-CTLA-4 or anti-CD28, respectively, and found that, compared with the anti-CD28-treated or untreated control mice, anti-CTLA-4 treated mice showed inhibited B7-51BLimlO tumor growth." (PMID 36604694, 2023). "We found that c-Jun overexpression enhanced T cell expansion driven by anti-CD3/CD28 magnetic beads, as well as TCR T cell expansion by tumor antigenic stimulation." (PMID 37215108, 2023). "Tumor-immune phenotypes related to FOXA1 were studied by focusing on six immune-related pathways, including CD28 co-stimulation, IL2 signaling, cell recruitment, cytokine–cytokine receptor interaction, interferon signaling, and IL12 signaling." (PMID 37958805, 2023). "Tumor-derived EVs containing miR-424 inhibit the expression levels of costimulatory molecule CD80 expressed on DCs and the expression of CD28 on Th cells and Tc cells, impairing T cell activation and proliferation." (PMID 37175226, 2023). "This occurs because the tumor cells express pHLA ligands that signal the TCR but they lack ligands required for T cell costimulation, via the CD28 or CD137 (41BB) pathway." (PMID 37810959, 2023). "Considering the critical role of TRM cells which exert a frontline defense against infections and contribute to anti-tumor immune response, we analyzed their frequency within total CD8+ T cells and the PD1/CD28 subsets, in the different districts." (PMID 37898752, 2023). "In contrast to the CD8 compartment, the amount of CD28- CD27+ TEMRA cells is significantly lower in CMV seronegative healthy donors compared to CMV seropositive healthy donors, while in tumor patients only a tendency of decreased amounts is observed." (PMID 36831183, 2023). "TCR triggering and CD28 co-stimulation upregulate CTLA4 in T cells, and tumor cell-intrinsic CTLA4 upregulation can be induced by β-catenin signaling." (PMID 37197667, 2023). "The presence of 4-1BB or CD28 in CAR increased the production of cytokines, and the 3G CAR-CIKs showed significant proliferation and long-term inhibition on tumor growth." (PMID 35903099, 2022). "Co-stimulatory ICMs CD28, CD80 and CD40LG are secondary signal molecules in the T lymphocyte activation, which activate patients’ anti-tumor immune responses, leading to increased efficacy of cancer immunotherapy." (PMID 35953696, 2022). "IL1R1 expression on blood Treg cells and IL1R1− tumour Treg cells was induced after 24 h of stimulation with anti-CD3, anti-CD28 and anti-CD2 beads (anti-CD3/CD28/CD2 beads)." (PMID 35545675, 2022). "There was also a large reduction in the proportion of CD28+CD69– cells (black clusters, red arrows) and an increase in the CD28+CD69+ cells (red dots) in the LAIT‐treated tumours, suggesting the differentiation and activation of CD8+ T cells following LAIT." (PMID 35808806, 2022). "These included genes consistent with pro-inflammatory immune responses (CD27, CD28, CD3e, CD8a, ICOS, ICOSLG, Pax5, TBX, GATA3, HLA-A, TNFSF14, GPR146), but also immune suppressive influences in the tumor immune microenvironment (CTLA-4, FoxP3, PD-1)." (PMID 36698398, 2022). "Although the total number of components of this CAR remains unchanged when compared to cMet-PD1/CD28-CAR, this type of CAR-T cells can also release some anti-tumor cytokines." (PMID 35392217, 2022). "The signaling domains of the co-receptor CD28 and 4-1BB affect the metabolic characteristics of human CAR-T cells, including enhancing cell persistence in the tumor microenvironment." (PMID 35965586, 2022). "Both 4-1BB and CD28, as well as the TACI and BAFF-R CAR treatments, exhibited similar tumor clearance and remission over 50 days." (PMID 36350984, 2022). "The results showed that CD30-28BBz CAR exhibited higher anti-tumor activity, better tumor homing and longer persistence than the second-generation CAR with CD28 only." (PMID 35729339, 2022).
tumor (continued). "When this PD-1:CD28 CSR was transduced together with a CAR or TCR into T cells, the engineered CTLs still interact with PD-L1 on tumor cells, but delivers a costimulation signal via CD28 rather than an inhibitory signal." (PMID 35432319, 2022). "Optimizing and improving the CAR structure for NK cells to improve the anti-tumor ability of CAR-NK cells, such as taking NKG2D as transmembrane domain, and using costimulatory molecules (2B4, CD28, 4-1BB)." (PMID 36032149, 2022). "For example, circulating MM tumor cells are characterized by lower expression of adhesion molecules (CD138, CD56, CD117, and others) and activation molecules (CD38, CD28, and CD81)." (PMID 35407416, 2022). "The intensity and distribution of CD69+, CD28+, and CD103+ expression on CD8+ T cells were all increased in the LAIT‐treated tumours." (PMID 35808806, 2022). "ICOS/ICOSL and CD28/B7-1/B7-2 are T cell co-stimulators and CTLA-4 is an immune checkpoint inhibitor that play critical roles in the pathogenesis of neoplasia." (PMID 36618349, 2022). "Consistently, CARs with two costimulatory domains (CD28-4-BB) targeting PSMA and mesothelin showed superior tumor eradication and increased persistence in solid tumor models compared with single domain-based CARs45,46." (PMID 35729339, 2022). "Compared with CAR-T cells containing CD28, CAR-T cells containing 4-1BB showed better T cell persistence and disease control because they expressed higher tumor antigen intensity." (PMID 35860578, 2022). "To analyze the magnetic accumulation of PBMCs and their effect on tumor spheroids, we unspecifically stimulated the PBMCs with CD3/CD28/CD2 for 3 days, and loaded them overnight with Cit-SPIONs." (PMID 36497463, 2022). "We also showed that CD28 and 4-1BB-based CAR-T cells exhibited comparable anti-tumor functions with different kinetics." (PMID 35252208, 2022). "A comparison of the effects of CD28 and 4-1BB costimulatory domains in CAR T- cell activation and interaction with tumor cells will be an important area for the future." (PMID 35681548, 2022). "In multiple tumor models, STAR-T exhibited similar persistence with 4-1BB-CAR-T and superior or equal antitumor effects compared with CD28-CAR-T." (PMID 35903099, 2022). "CD4+ T cells were sorted from tumors and tumor-draining lymph nodes of Tslp-PyMttg (test) or MMTV-PyMTtg, Tslpr(Crlf2)−/− (PyMttg TslprKO; control) mice and stimulated ex vivo using anti-CD3/CD28 antibodies plus TSLP over one to three cycles." (PMID 35657353, 2022). "While compared to the CD28 costimulation domain, the 4-1BB domain maintains less cytotoxicity, improves CAR-T proliferation, and improves efficiency when the tumour burden is high." (PMID 36299480, 2022). "Stimulation of Treg cells with anti-CD3 and anti-CD28 coated beads optimized for T cell activation led to a more pronounced increase in IL1R1 expression (up to 50% of blood Treg cells and IL1R1- tumour Treg cells)." (PMID 35545675, 2022). "The PBLs of patients with MPC had a significantly higher proportion of tumor-suppressive cytotoxic CD8+CD107a+ T cells and activated CD8+CD28+ T cells more than in patients with BPC." (PMID 36333670, 2022). "CTP hampered tumor development and enhanced the ratio of CD3e−NK1.1+ cells by 113.0% and CD3e+CD28+ cells by 84.7% in the peripheral blood of ApcMin/+ mice." (PMID 35662701, 2022). "We found CD28 CAR-T and 28BBz CAR-T cells displayed higher tumor lysis capacity than 4-1BBz CAR-T cells in vitro at an E:T ratio of 25:1 and then selected CD28 CAR-T and 28BBz CAR-T cells for in vivo antitumor assays." (PMID 35729339, 2022). "4-1BB-CAR-T cells also show better response to low-density antigens than CD28-CAR-T cells, which was demonstrated both in in vitro cytotoxic assays as well as in mouse tumour models." (PMID 36428480, 2022). "With higher affinity for B7 than CD28, excessive activation of the CTLA4 pathway leads to a decline in immune function and subsequent immune escape of tumor cells." (PMID 36042469, 2022).
tumor (continued). "Both CD28 and 4-1BB-based CAR-T cells can achieve complete tumor eradiation in clinical studies of refractory B cell malignancies." (PMID 35252208, 2022). "CD4+ T cells were sorted from tumors and tumor-draining lymph nodes of Tslp transgenic (test) or Tslpr knockout (TslprKO, control) mice and stimulated ex vivo using anti-CD3/CD28 antibodies plus TSLP." (PMID 36467403, 2022). "Splenocytes containing resultant tumor antigen-primed T cells were then collected and a subset had their activation reinforced ex vivo with anti-CD3/CD28 dynabeads." (PMID 36376929, 2022). "To determine the effector capacity of tumor-infiltrating T cells (TILs) from NC410-treated mice, we re-stimulated TILs from digested tumors with anti-CD3 plus anti-CD28 for 5 hr and performed intracellular staining to examine IFN-γ and TNF-α production." (PMID 34121658, 2021). "Subsequently, MDSCs isolated from ZQT-treated tumor-bearing mice (Z-MDSCs) or from control-treated mice (C-MDSCs) were incubated with purified T cells that were stimulated using CD3 and CD28 antibodies for 72 h." (PMID 33867859, 2021). "To further investigate the impact of CD103 expression on tumor-infiltrating CD3+ CD+ T cells, we stimulated tumor-infiltrating CD+ T cells through anti-CD3, anti-CD28, PMA and Ionomycin or anti-PD-1 in vitro for 12 h." (PMID 33934206, 2021). "All exceeded the 2G-A (CD28) CAR to direct sustained T cell expansion, tumor-cell killing, and cytokine release over multiple stimulation cycles." (PMID 35028604, 2021). "CTLA-4 outcompetes the co-stimulatory molecule CD28 for binding to B7-1/CD80 or B7-2/CD86 expressed on the surface of antigen presenting cells, including tumour infiltrating dendritic cells." (PMID 33995362, 2021). "Murine WASpL272P NK and T cells formed stable synapses with YAC-1 tumor cells and anti-CD3/CD28–coated beads, respectively." (PMID 33621210, 2021). "DCs have been shown to activate Tregs as well as Th17 cells in MM and promote tolerance to tumor antigens and T-cell evasion via interactions of CD80/CD86 with CD28 on tumor cells." (PMID 33717170, 2021). "Blocking PD-1/PD-L1 through mAb binding activates tumor-specific CD8+ T cells by allowing the activation of the TCR and CD28 co-stimulation with DCs, both in the TIME and the tumor-draining lymph node (tdLNs)." (PMID 34571982, 2021). "CD28 signaling inhibits CD73-mediated adenosine production and enables CD8+ T cells to acquire anti-tumor effector function." (PMID 34011962, 2021). "Splenocytes from mAb-treated mice were stimulated with plate-bound anti-CD3 and soluble anti-CD28 antibodies and cocultured with CFSE-labeled 4T1 or MC38 tumor cells at different ratios." (PMID 34673569, 2021). "It is engineered to have three antigen-binding sites to bind to tumor-specific antigens on tumor cells, CD3; a T cell receptor (TCR) on T cells, and CD28; co-stimulatory molecules, also expressed on T cells." (PMID 34072645, 2021). "Results showed that the levels of CD73 were significantly higher on CD28−CD8+ T cells than on CD28+CD8+ T cells isolated from the draining lymph nodes on day 8 and from tumors on day 20 after tumor implantation." (PMID 34011962, 2021). "Since primary human CD3 + T cells activated by anti-CD3/CD28 antibody-coated beads expressed CD137 and PD-1, reminiscent of TILs in tumour-bearing mice, we evaluated the binding of IBI319 to primary T cells." (PMID 34737267, 2021). "Here, we demonstrate that membrane proximity is critical for effective co-stimulation by CD28 and 41BB and present a parallel (p)CAR arrangement that exploits this principle to consistently deliver superior anti-tumor activity." (PMID 35028604, 2021). "Immunohistochemical staining for CD28 and CD8 was performed to assess the effect of CTL on tumor proliferation." (PMID 33988472, 2021).